BECN1 (beclin 1)
Diseases named in the same sentence as BECN1 in open-access papers (continued):
Sharing a sentence is not in itself a finding about the gene and the disease.
colon carcinoma (100 papers, 2010 to 2026). "Increased Beclin-1 expression was associated with better OS in patients with locally advanced colon carcinomas who received postoperative 5-FU chemotherapy for 6 months." (PMID 36160153, 2022). "It was proved that 5-fluorouracil (3 μM) as well as MM131 (1.5 and 3 μM) caused an increase in Beclin-1 concentration in HT-29 colon cancer cells." (PMID 33918514, 2021). "The overexpression of Beclin 1 is associated with a good prognosis in stage IIIB colon cancer, but with a poor prognosis in nasopharyngeal carcinoma." (PMID 24675697, 2014). "In this regard, we previously reported that Beclin 1 overexpression was associated with reduced survival in colon cancer patients treated with 5-fluorouracil as adjuvant therapy." (PMID 24956373, 2014). "Here, we also showed that the expression of BECN1 was lower in CRC samples than in adjacent normal tissues and was associated with poor prognosis in CRC, indicating that BECN1 could act as a suppressor and a novel prognostic marker for colon cancer patients." (PMID 32358527, 2020). "Furthermore, it has been shown that Beclin-1 deficiency is associated with increased angiogenesis when melanoma tumor cell lines are subjected to hypoxic conditions and that Beclin-1 expression disrupts the growth of colon cancer cells." (PMID 34201882, 2021). "Consistently, ectopic overexpression of BECN1 in colon cancer cell lines leads to growth inhibition, which is attributed to the low endogenous expression of this gene in these cancer cells." (PMID 40248706, 2025). "It is found that in colon cancer the significantly lower expression of BECN1 compared with the normal colon tissue was positively associated with poor prognosis in patients." (PMID 39768248, 2024). "Clinical studies have shown that a lack of autophagy-related proteins such as LC-3II, ATG5, and Beclin 1 can indicate poor prognosis in colon cancer patients." (PMID 38650627, 2024). "AMPK-mediated BECN1 phosphorylation at Ser90/93/96 promotes ferroptosis in human colon cancer cells by inhibiting the production of intracellular GSH." (PMID 37051693, 2023). "Beclin-1 Overexpression in cases with resected stage II and stage III colon carcinomas, who received 5-FU-based therapy was associated with worse OS, denoting a potential effect of autophagy in drug resistance." (PMID 36160153, 2022). "Previous studies have shown that Grias neuberthii extract can induce autophagy in human colon cancer cells by increasing intracellular Beclin-1 and LC-3 levels." (PMID 34976156, 2022). "The results indicated that H. pylori (CagA+) inhibited the expression of miR-125b-5p and promoted the expression of LC3B-II/LC3B-I and Beclin-1 in colon cancer cells." (PMID 33791049, 2021). "H. pylori (CagA+) inhibits miR-125b-5p and promotes LC3B-II/LC3B-I and Beclin-1 in colon cancer cells." (PMID 33791049, 2021). "An example of this is the increased expression of ATG7 as well as down-regulation of ATG5 and beclin-1 during apoptosis of colon cancer cells." (PMID 33467015, 2021). "Despite being the only study, which investigated miR-409-3p/Beclin 1 in OXA resistance, the findings suggest that this miRNA can enhance the chemosensitivity of colon cancer via Beclin 1 mediated autophagy inhibition." (PMID 33807355, 2021). "Previous reports suggest that the combination of BCG-CWS and IR induces the autophagy of colon cancer cells; moreover, this effect is reduced in colon cancer cells with a knockdown of Beclin 1 or Atg7." (PMID 33302414, 2020). "In colon cancer cells, ART treatment caused autophagy activation, evident by increasing LC3B-II and beclin-1 light chain levels and elevated numbers of autophagosomes." (PMID 33316936, 2020). "In colon cancer cells, Beclin-1 has been shown to be associated with EMT and invasive behaviours; loss of Beclin-1 was able to reverse this phenotype." (PMID 32226927, 2020).
colon carcinoma (continued). "Specifically, inhibition of autophagy using 3‐MA treatment reduced the growth rate of colon cancer cells, whereas treatment with CQ or knockdown of Beclin‐1 in fibroblasts prevented the increase in HNSCC proliferation in cocultures." (PMID 30302772, 2019). "Altogether, our data confirms that RCE induces a Beclin-1 independent autophagy in colon cancer cells." (PMID 28912474, 2017). "With 5-fluorouracil treatment, colon cancer patients with higher expression of Beclin 1 had poorer overall survival." (PMID 28881721, 2017). "Taken together, these data provide convincing evidence that exposure of colon cancer cells to Rhus coriaria triggers a Beclin-1 independent autophagy." (PMID 28912474, 2017). "Although this finding appears similar to As2O3 in colon cancer cell death it is different from As2O3-induced cell deaths, which is Beclin-1-independent autophagic cell death." (PMID 28355296, 2017). "The repression of colon cancer cell proliferation in xenograft models was observed upon the induction of apoptosis and inhibition of proliferation by in vivo Beclin 1 expression, whereas BECN-1 plays a complex role in CRC." (PMID 40723786, 2025). "In the present study, total Bcl-2 levels and Beclin-1–Bcl-2 complex formation decreased upon treatment of colon cancer cells with the KRG extract, both indicating the participation of the Bcl-2 signaling pathway in the KRG extract-induced autophagy-mediated cell death." (PMID 36079818, 2022). "Therefore, the overexpression of BECN1 can suppress proliferation, invasion and induce apoptosis in our model of colon cancer." (PMID 36555736, 2022). "We demonstrated that the novel compound was able to induce apoptosis through intrinsic and extrinsic pathways and was capable of decreasing sICAM-1, mTOR, cathepsin B concentrations, whereas increased Beclin-1 concentration was detected in both colon cancer cell lines." (PMID 33918514, 2021). "The study was evidence that Beclin-1 acts as a molecule target for the treatment of colon cancer." (PMID 33918514, 2021). "The autophagy gene, Beclin-1, had been studied in stomach, ovaries, esophagus, and colon cancers." (PMID 33906303, 2021). "In addition, the level of Beclin-1 was higher in relapsed colon cancer than that in untreated colon cancer tissues or adjacent tissues." (PMID 31896739, 2020). "Besides, overexpression of miR-409-3p has the power to enhance the chemosensitivity of colon cancer cells by depressing Beclin-1-induced autophagy." (PMID 32662828, 2020). "Similarly, we found, in the present study, that RCE induced both depletion of Beclin-1 through proteasome degradation and Beclin-1-independent autophagy in colon cancer cells." (PMID 28912474, 2017). "In colon cancer, Beclin 1 was an adverse factor for 5-fluorouracil treatment." (PMID 28881721, 2017). "In addition, knockdown of Beclin 1, a key regulator of autophagy induction, using two different targeting sequences abolished the pro-survival effect mediated by adipocytes in colon cancer cells." (PMID 28151470, 2017). "Similarly, in two lines of primary colon cancer cells (patient-derived), icaritin (10 μM) treatment induced Beclin-1, ATG-5 and LC3B-II upregulation but p62 degradation." (PMID 28103582, 2017). "In a recent study on 178 colon carcinomas treated with adjuvant 5-FU, Beclin-1 overexpression (but not p62) was significantly associated with worse OS." (PMID 27444698, 2016). "In addition, ectopic expression of the BECN1 gene or UVRAG have both been shown to suppress the growth of xenografts of human colon cancer cell lines, suggesting that autophagy plays a tumor-suppressive role in tumorigenesis." (PMID 26965179, 2016). "A recent study showed that both BECN1 over- and under-expression could be related to poor colon cancer prognosis, illustrating the multifunctionality of BECN1 and autophagy in cancer aggressiveness." (PMID 27203674, 2016).
colon carcinoma (continued). "Similar results were also found in other human malignancies, such as esophageal, hepatocellular and colon cancers and high-grade glioma, in which down-regulated expression of Beclin 1 was frequently observed in more aggressive tumor subgroups and had a worse prognosis." (PMID 23573264, 2013). "In colon cancer, extensive overexpression of Beclin 1, a protein required for the formation of autophagosomes, has been 21.3% of cases, respectively, in which extensive overexpression is associated with high histological grade, vascular invasion, nodal involvement and poorer overall survival." (PMID 22679478, 2012). "In addition, ABHD5 could also interact with BECN1 to regulate the autophagy and tumorigenesis of colon cancer cells." (PMID 31799599, 2019). "Researchers found that higher BECN1 expression was observed in patients with surgically resected stage II and III colon tumors who underwent 5-FU treatment, leading to poorer overall survival." (PMID 40723786, 2025). "In human colon cancer cell lines, AMPK early activation promoted autophagy by phosphorylating beclin-1, while late activation led to pronounced apoptosis by caspase-8-dependent cleavage of beclin-1." (PMID 39929794, 2025). "Consistent with our previous findings in colon cancer cells, RCE treatment decreased Beclin-1 levels in a concentration-dependent manner in Panc-1 and Mia-Paca-2 cells." (PMID 39139643, 2024). "MM124 and MM137 decreased the concentrations of LC3A, LC3B, and Beclin-1 in the tested DLD-1 and HT-29 colon cancer cell lines, but strongly induced programmed cell death." (PMID 37047765, 2023). "It was observed that the expression of Beclin-1 and LC3B-II proteins was higher in BR colon cancer cells than that in AT1.6 cells." (PMID 34829834, 2021). "It was discovered that chloroquine and oxaliplatin interact synergistically on colon cancer cell lines, which confirmed the silencing of ATG5 through RNA interference, whereas the incubation of cells with beclin-1 resulted in the inhibition of autophagy." (PMID 33467015, 2021). "Experiments using multidrug treatment of colon cancer cells indicated that AMPK activation promoted apoptosis by phosphorylating Beclin-1 at Ser93/96, which increases Beclin-1 cleavage by caspase-8." (PMID 35054445, 2021). "In our experiment, we determined Beclin-1 levels and showed that MM131 efficiently increased Beclin-1 concentrations in both DLD-1 and HT-29 colon cancer cells." (PMID 33918514, 2021). "Our immunoblotting results suggest that polydatin stimulates autophagy-related proteins, including phosphorylated ULK1, BECN1, ATG5, and LC3B, and has a protective effect against colon cancer." (PMID 34573109, 2021). "For the top colon cancer MEGs, the consistent tumor suppressor genes included MAP2K4, MAPK10, RUNX3, WNK2 (the four genes were identified by the TSGene 2.0 database), BECN1, FASN, NAT1, and NR3C2." (PMID 33273919, 2020). "The tolerance of colon cancer cell lines to oxaliplatin involves the down-regulation of Bcl2-modifying factor (BMF), ATG7, and Beclin-1." (PMID 31658599, 2019). "Autophagy-related proteins, including Beclin-1, ATG5, and LC3-II, are downregulated in 5-FU-resistant human colon cancer cells." (PMID 31658599, 2019). "It was found that ABHD5 binds to and prevents the cleavage of the essential autophagy regulator Beclin 1 (BECN1), thus stimulating autophagy, which reduces colon cancer tumorigenesis." (PMID 30081476, 2018). "In the present study, the effect of KRAS/BRAF/PIK3CA oncogenic pathways on the autophagic cell properties and on main components of the autophagic machinery like p62 (SQSTM1), Beclin-1 (BECN1) and MAP1LC3 (LC3) in colon cancer cells was investigated." (PMID 26802026, 2016).
colon carcinoma (continued). "Other previous studies have also found that autophagy-related proteins were upregulated in colon cancer, as assessed by an increase in LC3 or BECN1 expression in a significant proportion of primary tumors." (PMID 24723943, 2014). "A key observation was that Beclin 1 and UVRAG can regulate centrosome stability in colon cancer cells." (PMID 24956373, 2014). "Decreased Beclin-1 expression is frequently seen in malignant cells such as breast, esophageal, gastric, cervical, and stage III colon cancer cells, with a poor prognosis." (PMID 24282606, 2013). "Interestingly, this study reported a significant decrease in both autophagy markers, LC3-II, and Beclin-1, in HCT116 colon cancer cells following 5-FU (5-Fluorouracil) treatment." (PMID 41346768, 2026). "Interestingly, a previous study demonstrated that while BECLIN-1 knockdown disrupted OCCLUDIN trafficking, it unexpectedly reduced TJ permeability in Caco-2 colon cancer cells grown in 2D cultures." (PMID 40395982, 2025). "RCE was found to induce Beclin-1-independent autophagy and caspase 7-dependent apoptosis through proteasome-mediated degradation of Beclin-1, mTORC1, and AKT, and pro-caspase-3, respectively in colon cancer cells." (PMID 39139643, 2024). "In addition, the analogue 17-hydroxy Wortmannin decreases drug resistance by restoring TRAIL’s response through ameliorating PIK3C3-beclin 1 (BECN1) complex and autophagy activity in colon cancer cells." (PMID 36034776, 2022). "Trachelogenin (5–10 μM), a lignan isolated from Combretum fruticosum, promoted autophagic cell death, but not apoptosis, as shown by the appearance of AVOs and autophagic vacuoles, by the increase in Beclin 1 expression and by the conversion of LC3 I into LC3 II in HCT-116 colon cancer cells." (PMID 32927836, 2020). "Moreover, reduced levels of Beclin 1 protein have been correlated to poor patient outcome in many tumor types, such as esophageal cancer, stage III colon cancer, hepatocellular carcinoma and high-grade glioma." (PMID 20454448, 2010). "We also assessed the levels of Beclin-1, a component of the PI3KC3 autophagic complex, as previously we reported contrasting results: canonical Beclin-1-dependent autophagy in triple negative breast cancer and non-canonical Beclin-1-independent autophagy colon cancer cells." (PMID 39139643, 2024). "However, restoration of nuclear Beclin 1 can not fully rescue BECN1 silencing-mediated reduction of colon cancer cell colony formation." (PMID 36230664, 2022). "In addition, the expression of Beclin-1, which is involved in the initiation phase of autophagy, also increased in BR colon cancer cells compared to that in their respective PT, AT1.6, and AT6.4 colon cancer cells." (PMID 34829834, 2021). "To determine whether RACK1-induced autophagy promotes colon cancer cell proliferation and inhibits colon cancer cell apoptosis, we used siRNA against ATG5 or BECN1 to inhibit autophagy in the RACK1 OE colon cancer cells, and analyzed the changes of cells proliferation and apoptosis." (PMID 30451832, 2018). "Furthermore, we found that this early event serves as a trigger for the induction of non-canonical Beclin-1-independent autophagy and subsequent autophagy-dependent caspase-7-dependent apoptosis which ultimately leads to cellular death of colon cancer cells." (PMID 28912474, 2017). "However, BIX01294 induced changes could be cell-type specific, as in human colon cancer HCT116 cells the expression of LC3B, ATG9A, ATG4A, but not ATG4B/C, ATG7, BECN1, WIPI1 was increased after BIX01294 treatment." (PMID 27934912, 2016).
glioma (80 papers, 2012 to 2026). A benign or malignant brain and spinal cord tumor that arises from glial cells (astrocytes, oligodendrocytes, ependymal cells). "N25 induces autophagy in glioma cells through a new mechanism of upregulating Tip60 by inhibiting HDAC3, causing upregulation of ULK1 (Atg1) and Beclin-1 (Atg6), and resulting in induction of glioma cell autophagy." (PMID 29088860, 2017). "Several studies suggest that reduced beclin-1/autophagy markers may reflect impaired autophagic pathways (including autophagic cell death) and can associate with aggressive disease biology in subsets of glioma cohorts." (PMID 41511337, 2025). "Therefore, we proposed a hypothesis that N25 induces autophagy probably through a new mechanism of upregulating Tip60 by inhibiting HDAC3, causing upregulation of ULK1 (Atg1) and Beclin-1 (Atg6), and resulting in induction of glioma cell autophagy." (PMID 29088860, 2017). "As it was mentioned before, we had discovered that under specific conditions of blocking the intracellular survival pathways, the complex of Bcl-2 and beclin-1 proteins was a specific trigger for apoptotic dominant glioma cell elimination." (PMID 41511337, 2025). "Several glioma-focused experimental and clinical studies implicate beclin-1 expression and Bcl-2 family regulation in GBM biology so far." (PMID 41511337, 2025). "A well-known example, described in malignant glioma cells by our team before, of this crosstalk is the interaction between the anti-apoptotic protein Bcl-2 and the autophagy regulator beclin-1." (PMID 41511337, 2025). "Conclusions: “Switching” between apoptosis and autophagy using PI3K and Raf inhibitors with Bcl-2:beclin-1 complex formation opens new therapeutic perspectives against gliomas." (PMID 38067099, 2023). "The aim of this research was to investigate the role of Bcl-2:beclin-1 complex in glioma cell elimination through the combined action of LY294002 and sorafenib." (PMID 38067099, 2023). "Studies have shown that CISD2 expression is increased in glioma and it can induce the proliferation of glioma cells through inhibiting beclin-1-mediated autophagy." (PMID 35493303, 2022). "We further demonstrated that Sev treatment suppressed the expression of GPX4, while upregulating the expression of transferrin and ferritin and Beclin-1 in glioma cells in a dose-dependent manner." (PMID 35372041, 2022). "It was explained that knockdown of ATG7 and Beclin 1, which are essential autophagy genes, sensitized the glioma cells in vitro." (PMID 33525678, 2021). "In U343 glioma cells, adenovirus-mediated shRNA inhibiting c-Met can induce autophagy that is characterized by many vacuolated cells, upregulated Beclin-1 expression, and recruitment of MAP1LC3." (PMID 34204169, 2021). "TFEB has been reported to be overexpressed in high-grade gliomas along with the extra genes coding for the autophagy proteins, such as Beclin 1, LC3A, LC3B, Ulk 1, Ulk 2, p62 and sequestome 1 (SQSTM1)." (PMID 33525678, 2021). "In the same direction, beyond the gene signatures, it has been shown that higher expression levels of the ATG proteins: LC3, Beclin-1, and p62 are more prevalent in IDHwt gliomas in than IDHmut gliomas." (PMID 34178638, 2021). "We also further evaluated a range of autophagy-related proteins, including mTOR, p-mTOR, ATG5, ATG12 and Beclin-1 in glioma cells." (PMID 34683892, 2021). "On the other hand, a higher expression of LC3/Beclin-1 correlated with a shorter progression-free survival in low- and high-grade glioma patients." (PMID 32707662, 2020). "Firstly, repaglinide possesses cytotoxic effects against hepatic, breast and cervical carcinoma cells (HepG2, MCF-7 and HeLa cells), or reduces the expression of Bcl-2, Beclin-1 and PD-L1 in glioma tissues." (PMID 33382703, 2020). "Regarding this, we observed that autophagy induction by rapamycin leads to decreased expression of pCdk5 and an increase in Beclin 1 protein expression levels in glioma cells." (PMID 30899038, 2019).